TBC1D3D (TBC1 domain family member 3D)
Description:
Acts as a GTPase activating protein for RAB5. Does not act on RAB4 or RAB11 (By similarity).
Synonyms: PRC17; TBC1D3
Gene: Protein-coding gene on chromosome 17 (38,003,976 to 38,014,908, forward strand). Ensembl gene ENSG00000274419.
Subcellular location: Cell membrane
Subcellular location (Human Protein Atlas): Vesicles
Gene Ontology:
Molecular function: GTPase activator activity
Cellular component: plasma membrane; endosome; membrane
Homologues: Orthologues: chimpanzee TBC1D3B (97% identical). Paralogues in human: TBC1D3 (99% identical), TBC1D3C (99% identical), TBC1D3I (99% identical), TBC1D3H (99% identical), TBC1D3L (99% identical), TBC1D3E (99% identical), TBC1D3F (99% identical), TBC1D3G (99% identical), TBC1D3K (99% identical), TBC1D3B (99% identical), TBC1D26 (30% identical), USP6NL (29% identical), and 33 more.
Diseases named in the same sentence as TBC1D3D in open-access papers:
TBC1D3D is named in the same sentence as 4 diseases in open-access papers, as found by Europe PMC text mining. Sharing a sentence is not in itself a finding about the gene and the disease. The quoted sentences say what the papers report.
clear cell renal cell carcinoma (1 paper, 2021). "In addition, TBC1D3D may positively regulate proliferation, and overexpression of TBC1D3 promoted clear cell renal cell carcinoma proliferation in vitro." (PMID 34553038, 2021).
TBC1D3D also shares sentences with these, for which no sentence is quoted: cancer (1 paper); lung adenocarcinoma (1); tumor (1).